IGF2BP1 (insulin like growth factor 2 mRNA binding protein 1)
Diseases named in the same sentence as IGF2BP1 in open-access papers (continued):
Sharing a sentence is not in itself a finding about the gene and the disease.
breast cancer (continued). "Furthermore, by MeRIP-seq and experimental verification, we found that IGF2BP1 directly recognized and bound to the m6A sites on CPT1A mRNA and enhanced its stability, which ultimately mediated IGF2BP1-induced breast cancer metastasis." (PMID 36632454, 2023). "Therefore, our study suggests that RUNX1-IT1 is a novel oncogenic lncRNA in breast cancer, dysregulation of RUNX1-IT1/IGF2BP1/GPX4 is responsible for breast cancer carcinogenesis and progression." (PMID 37036576, 2023). "MIR210HG promotes breast cancer progression through m6A modification mediated by IGF2BP1." (PMID 36844874, 2023). "A role for IGF2BP1 in breast cancer, however, remains controversial." (PMID 36092925, 2022). "We additional analyzed the prognostic relevance of IGF2BP1 in breast cancer by applying enrichment analysis of DEGs, and our data revealed the involvement of pathways such as glucuronidation, cytochrome P450 (CYP) enzyme-related drug metabolism, cornification, and keratinization." (PMID 36092925, 2022). "In addition, the expression of IGF2BP1 was identified positively correlated to MYCN expression in breast cancer." (PMID 35346372, 2022). "In addition to discriminating cancerous from normal cells, the mRNA levels of IGF2BP1 were found to be significantly increased in certain subgroups of breast cancer." (PMID 36092925, 2022). "The MYCN/IGF2BP1/MIR210HG axis may serve as an alternative molecular mechanism of breast cancer progression." (PMID 35346372, 2022). "From analysis of TCGA-BRCA datasets, IGF2BP1 was confirmed to be highly expressed in breast cancer." (PMID 35346372, 2022). "Therefore, it is crucial to elucidate the detailed expression patterns of IGF2BP1 in heterogeneous breast cancer." (PMID 36092925, 2022). "Further analyses indicated that IGF2BP1 may be a key m6A RNA methylation regulator in breast cancer." (PMID 34141492, 2021). "The results showed that knockdown of IGF2BP1 led to reduced c-Myc mRNA stability, and ectopic IGF2BP1 could further increase c-Myc mRNA stability in normoxic breast cancer cells." (PMID 33469161, 2021). "Previous studies found that IGF2BP1 is highly expressed in breast cancer." (PMID 34044876, 2021). "This suggested that lncRNA KB-1980E6.3 could recruit IGF2BP1 to retain c-Myc mRNA stability in hypoxic breast cancer cells." (PMID 33469161, 2021). "The newly identified lncRNA KB-1980E6.3/IGF2BP1/c-Myc axis may potentially be a therapeutic target for breast cancer." (PMID 33469161, 2021). "In addition, endogenous IGF2BP1 levels remained the same in lncRNA KB-1980E6.3 knockdown breast cancer cells under nomorxia and hypoxia." (PMID 33469161, 2021). "LncRNA KB-1980E6.3 maintained breast cancer stem cell stemness via interacting with IGF2BP1." (PMID 34917609, 2021). "Patients with high IGF2BP1 expression in breast cancer have a worse prognosis." (PMID 31897227, 2020). "Further analysis of TCGA data, we found that IGF2BP1 is highly expressed in breast cancer." (PMID 31897227, 2020). "However, the tumor-suppressive role of IGF2BP1 has been observed in breast cancer and colon stromal cells." (PMID 29954406, 2018). "At least in breast cancer, it is confirmed that IGF2BP1 inhibits tumor cell growth and invasion." (PMID 29954406, 2018). "However, inconsistent with the suppressive role in the breast tumor cell-derived cell and xenograft mouse models, some in vivo studies revealed that IGF2BP1 plays an enhancive role in tumorigenesis and metastasis in breast cancer cells." (PMID 29954406, 2018). "IGF2BP1 activation may depress chemotaxis and metastasis of breast cancer cells through sustaining cell polarity and directional movement by modulating the localization of β-actin mRNA." (PMID 29954406, 2018).
breast cancer (continued). "However, the suppression of invasion and metastasis by IGF2BP1 was seen in breast carcinoma cells of human and rat." (PMID 29954406, 2018). "To address this in further detail, we transduced breast cancer-derived MCF7 cells, which express IGF2BP1 at barely detectable levels, with lentiviral vectors encoding either GFP or GFP-fused ZBP1, the chicken ortholog of IGF2BP1." (PMID 23677615, 2013). "However, the prognostic relevance of IGF2BP1 in breast cancer remains debatable." (PMID 36092925, 2022). "Therefore, the MYCN/IGF2BP1/MIR210HG axis may serve as an alternative molecular mechanism of breast cancer progression." (PMID 35346372, 2022). "Our data revealed IGF2BP1 at differential levels among intrinsic subtypes of breast cancer (Normal, n = 40; LumA, n = 562; LumB, n = 204; Basal, n = 195; Her2, n = 82: Kruskal–Wallis test, p < 0.001), which raised the question whether IGF2BP1 was related to breast cancer prognosis." (PMID 36092925, 2022). "Thus, a low ratio of lncRNA KB-1980E6.3/IGF2BP1 was found under normoxia, and hypoxia-induced high level of lncRNA KB-1980E6.3 resulted in a high lncRNA KB-1980E6.3/IGF2BP1 ratio under hypoxia, which was reduced in accompany with lncRNA KB-1980E6.3 knockdown in hypoxic breast cancer cells." (PMID 33469161, 2021). "Moreover, lncRNA KB-1980E6.3 plays an essential role for BCSCs stemness by enhancing c-Myc mRNA stability via interaction with IGF2BP1, which may provide breast cancer cells with more flexibility to adapt to hypoxic environmental conditions." (PMID 33469161, 2021). "IGF2BP1 may be a key m6A RNA methylation regulator in breast cancer." (PMID 34141492, 2021). "IGF2BP1 directly recognizes and binds to the m6A site on CPT1A mRNA, increasing its stability and mediating IGF2BP1-induced breast cancer metastasis; this mechanism has been verified in clinical samples." (PMID 41219902, 2025). "IGF2BP1 is stabilized by deubiquitination mediated by Ubiquitin-Specific Peptidase 10 (USP10), resulting in its elevated expression in breast cancer." (PMID 39342406, 2024). "LncRNA FGF13-AS1 disrupts the interaction between IGF2BP1 and Myc mRNA through the FGF13-AS1/IGF2BP1/Myc axis, inhibiting glycolysis and stemness of breast cancer cells." (PMID 39062595, 2024). "CircPTPRA competitively binds to the KH domain of IGF2BP1, interfering with its interaction with the downstream targets Myc and FSCN1 mRNA, thus inhibiting the growth and invasiveness of breast cancer cells." (PMID 39062595, 2024). "In clinical samples, USP10 levels correlated with IGF2BP1 and CPT1A levels, and breast cancer patients with high levels of USP10, IGF2BP1, and CPT1A had the worst outcome." (PMID 36632454, 2023). "Collectively, our data reveal that RUNX1-IT1 promotes breast cancer tumorigenesis through inhibiting ferroptosis via regulating IGF2BP1/GPX4 axis, providing a potential prognostic marker and therapeutic target for breast cancer." (PMID 37036576, 2023). "IGF2BP1 was confirmed highly expressed in breast cancer and induced both MIR210HG and miR-210 expression, which contributed to breast cancer progression." (PMID 35346372, 2022). "The confirmed interaction of IGF2BP1 and MIR210HG provides an extended explanation of the molecular mechanism in breast cancer progression." (PMID 35346372, 2022). "According to the literature review, USP3 promotes GC cell migration and invasion; SLC7A6 hasn’t been reported in studies related to cancer; IGF2BP1 accelerates GC progression; and TKT facilitates breast cancer metastasis." (PMID 35739527, 2022). "Upregulated lncRNA KB1980E6.3 forms lncRNA KB-1980E6.3/IGF2BP1/C-MYC signal axis by absorbing IGF2BP1, which maintains the stability of C-MYC mRNA and leads to poor prognosis of breast cancer." (PMID 36237306, 2022). "In conclusion, IGF2BP1 induces MIR210HG through m6A modification, through which IGF2BP1 functions as an oncogene in breast cancer." (PMID 35346372, 2022).
breast cancer (continued). "Therefore, IGF2BP1 may serve as a target for breast cancer treatment." (PMID 34141492, 2021). "In T47D cells, silencing IGF2BP1 resulted in increased levels of UCA1 and thereafter increased the expression of miR-122-5p target mRNAs, eventually prompting breast cancer cell invasion." (PMID 34044876, 2021). "With the increase of malignancy of breast cancer, the expression level of several m6A RNA methylation regulators, such as FTO, HNRNPA2B1 YTHDC1, IGF2BP1, IGF2BP2 and IGF2BP3, decreased or increased." (PMID 34141492, 2021). "After comparing breast cancer tissues with adjacent normal tissues, we found IGF2BP1 and IGF2BP3 had a fold change >2 in breast cancer tissues." (PMID 34141492, 2021). "The interplay of IGF2BP1 and CTNNB1-dependent signaling was moreover suggested to negatively regulate the migration of breast cancer-derived cells in vitro." (PMID 23677615, 2013). "One simple explanation is that what is described to be IGF2BP1 in T47D is a specific IGF2BP1 mutant/isoform or another IGF2BP paralogue, since IGF2BP1 expression is barely observed in a panel of breast cancer-derived cells including T47D." (PMID 23069990, 2013). "With the exception of breast carcinoma-derived MDA-MB-231 cells, IGF2BP1 expression was well correlated with the expression of the mesenchymal marker vimentin (VIM)." (PMID 23677615, 2013). "RUNX1 intronic transcript 1 binds to the N6-methyladenosine m6A reader IGF2BP1, promotes the formation of the IGF2BP1 biomolecular condensate, and improves the stability of GPX4 mRNA, which increases the expression of GPX4, blocks ferroptosis, and promotes breast cancer development." (PMID 40642070, 2025). "In addition, IGF2BP1 can directly identify, bind and stabilise the m6A region on CPT1A mRNA, which in turn mediates IGF2BP1‐induced breast cancer metastasis." (PMID 39679845, 2024). "IGF2BP1 could recognize and bind to the m6A sites on CPT1A mRNA, promoting the N6-methyladenosine modification and breast cancer metastasis." (PMID 39430239, 2024). "Specifically, IGF2BP1 maintains the stability of MYC by binding to the coding region determinant of m6A-modified MYC in a hypoxic microenvironment, thereby promoting the self-renewal of breast cancer stem cells." (PMID 37554271, 2023). "First limitation was the lack of validation of the relative expression of IGF2BP1, its prognostic relevance in breast cancer, and the predictive capability of our established nomogram using external datasets such as large, multicenter cohorts." (PMID 36092925, 2022). "Q-PCR and western blot analysis indicated that IGF2BP1 was highly expressed in breast cancer cells compared to normal cell, implying that IGF2BP1 was positively correlated to breast cancer." (PMID 35346372, 2022). "To elucidate the role of IGF2BP1 in breast cancer, we first interrogated large publicly available datasets from METABRIC using cBioPortal and analyzed genetic alterations in IGF2BP1 that included mRNA amplifaction, deletion or level changes and their correlation with clinical values." (PMID 36092925, 2022). "In addition, both IGF2BP1 and ELAVL1 enhance the stability of MIR210HG, which contributes to the progression of breast cancer." (PMID 35346372, 2022). "Research in mouse xenograft models demonstrated that IGF2BP1 inhibits pulmonary metastatic tumours of breast cancer, while other research showed that IGF2BP1 does not affect tumour growth or size." (PMID 34044876, 2021). "IGF2BP1, IGF2BP2 and IGF2BP3, members of the IGF2BP family, modulate RNA splicing, translation, processing, and stability and thereby affect cell proliferation, differentiation, invasion and metastasis in breast cancer." (PMID 34044876, 2021). "Taken together, our data reveal that RUNX1-IT1 promotes breast cancer carcinogenesis through blocking ferroptosis via elevating GPX4, targeting of the previously unappreciated regulatory axis of RUNX1-IT1/IGF2BP1/GPX4 may be a promising treatment for patient with breast cancer." (PMID 37036576, 2023).
breast cancer (continued). "Further research is needed to determine how IGF2BP1 and RUNX1-IT1 interact with each other and their specific binding regions, so as to design some oligonucleotides or peptides to block their binding, which may be a novel therapeutic strategy for breast cancer." (PMID 37036576, 2023). "Research in mouse xenograft models demonstrated that IGF2BP1 inhibits cell proliferation, tumour growth and tumour metastasis of breast cancer by binding to the 3′UTR of GDF15 mRNA, while other research showed that IGF2BP1 does not affect tumour growth or size." (PMID 34044876, 2021).
hepatocellular carcinoma (56 papers, 2012 to 2026). A malignant tumor that arises from hepatocytes. "In HCC, the up-regulation of the lncRNA HULC (hepatocellular carcinoma up-regulated long noncoding RNA) was associated with the depletion of IGF2BP1, which recognizes m6A-modified HULC molecules and recruits the CCR4-NOT complex to initiate HULC degradation." (PMID 40584291, 2025). "Ectopic expression of IGF2BP1 in chicken liver-related cell line Leghorn strain M chicken hepatoma (LMH) cell revealed that IGF2BP1 can regulate the expression of genes associated with fatty acid metabolism." (PMID 31208008, 2019). "RBM15 modulates m6A modification of YES proto-oncogene 1 (YES1) mRNA in an IGF2BP1-dependent manner, promoting hepatocellular carcinoma progression, indicating RBM15/IGF2BP1 regulates the m6A modification of other genes in other diseases." (PMID 40592832, 2025). "RBM15 can also regulate YES1 m6A modification in an IGF2BP1-dependent manner, promoting the development of hepatocellular carcinoma." (PMID 40435202, 2025). "IGF2BP1 can regulate the invasion, migration, growth and proliferation of hepatocellular carcinoma (HCC) cells by long non-coding RNA LIN28B-AS1 regulation." (PMID 39028290, 2024). "The highly expressed circMAP3K4 encoded circMAP3K4‐455aa, which was driven by m6A modification, the m6A “reader” protein IGF2BP1, promoted hepatocellular carcinoma (HCC) progression by preventing HCC cells from cell death under stress." (PMID 37669906, 2023). "Linc01093 triggered the mRNA decay of GLI1 through interaction with IGF2BP1 to suppress hepatocellular carcinoma (HCC progression." (PMID 36221055, 2022). "LncRNA HCG11 effectively promoted tumor cell growth and metastasis in hepatocellular carcinoma by interacting with IGF2BP1." (PMID 34949159, 2022). "Previous research has illustrated that the expression of IGF2BP1 promotes hepatocellular carcinoma cell proliferation, migration, and invasion, and correlates with poor survival rate." (PMID 33796449, 2021). "In another report, miR-625-5p targeted IGF2BP1 to inhibit the migration and invasion of hepatocellular carcinoma." (PMID 30988674, 2019). "miR-625 suppresses hepatocellular carcinoma migration and invasion by targeting IGF2BP1 and further affects the IGF2BP1/PTEN pathway." (PMID 27588393, 2016). "LIN28B-AS1 targeted binding to IGF2BP1, thus promoting the malignant phenotype in hepatoma cells." (PMID 37304234, 2023). "IGF2BP1 has been identified as an unfavorable prognostic indicator in tumors such as lung adenocarcinoma, endometrial cancer, gastric cancer, hepatocellular carcinoma, and serous ovarian cancer." (PMID 37280679, 2023). "For example, hsa-miR-150/IGF2BP1 regulatory pair was reported to be a novel potential therapeutic target for osteosarcoma treatment, and IGF2BP1 was identified as a novel target gene of hsa-miR-98-5p in hepatocellular carcinoma." (PMID 33718187, 2021). "Notably, one transcript, the proliferation marker Ki-67 (MKI67), is stabilized by IGF2BP1 in hepatocellular carcinoma." (PMID 32761127, 2020). "IGF2BP1 is a known pro-tumorigenic factor in traditional hepatocellular carcinoma." (PMID 28486549, 2017). "Additional studies found that the transcription factor YY1 (yin yang 1) together with LINC01134, miR-324-5p, and IGF2BP1 (Insulin-like growth factor 2 mRNA binding protein 1), could form a positive feedback loop that mediates the progression of hepatocellular carcinoma." (PMID 37914721, 2023). "CircMAP3K4, which encodes the peptide circMAP3K4-455aa, was also found in hepatocellular carcinoma, and circMAP3K4-455aa promoted HCC growth in vitro and in vivo, in which circMAP3K4 translation is dependent on m6A modification and is mediated by the recruitment of IGF2BP1, which is an E3 ligase." (PMID 36139159, 2022). "IGF2BP1 expression has been reported in gallbladder cancer (GC), hepatocellular carcinoma (HCC), and fibrolamellar hepatocellular carcinoma (FL-HCC)." (PMID 29954406, 2018).